GAS1RR (GAS1 adjacent regulatory RNA)
Synonyms: LncRNA-Hh; RP11-276H19.1
Gene: Long non-coding RNA gene on chromosome 9 (86,948,583 to 87,013,294, forward strand). Ensembl gene ENSG00000226237.
Diseases named in the same sentence as GAS1RR in open-access papers:
GAS1RR is named in the same sentence as 5 diseases in open-access papers, as found by Europe PMC text mining. Sharing a sentence is not in itself a finding about the gene and the disease. The quoted sentences say what the papers report.
breast invasive carcinoma (1 paper, 2022). "The pearson correlation coefficient of circRNA/lncRNA-mRNA expression was greater than 0.6(p<0.05) According to starbase database, LINC02381-hsa-miR-1301-5p and GAS1RR-hsa-miR-3619-5p exhibited negative correlation in 1,085 breast invasive carcinoma samples." (PMID 35391800, 2022).
mesothelioma (1 paper, 2019). A usually malignant and aggressive neoplasm of the mesothelium which is often associated with exposure to asbestos. "In the ceRNA networks, GAS1RR, AXIN2, AC017104.1, RASSF8-AS1, CGN, MIR4458HG, has-miR-125b-5p, LINC01105, and CASP9 were significantly associated with overall survival in mesothelioma." (PMID 31681739, 2019).
cancer (1 paper, 2020). A tumor composed of atypical neoplastic, often pleomorphic cells that invade other tissues. "Three down-regulated dp-lncRNA genes, GAS1RR, RPL34-DT, and RAP2C-AS1, were reported to be implicated in cancer." (PMID 32079618, 2020).
tumor (1 paper, 2024). "MSC-AS1, AC087222.1, CDKN2A-AS1, AC009121.2 and CSTF3-AS1 had increased expression in HNSC cells, whereas ZNF710-AS1, GAS1RR, and EP300-AS1 had decreased expression in OSCC tumor cells." (PMID 39052123, 2024).
GAS1RR also shares sentences with these, for which no sentence is quoted: prostate carcinoma (1 paper).